AR (androgen receptor)
Diseases named in the same sentence as AR in open-access papers (continued):
Sharing a sentence is not in itself a finding about the gene and the disease.
cancer (continued). "miR-145-5p has been found to suppress cancer cell proliferation, invasion, stemness, chemotherapy, and radiation sensitivity in patients with PCa by targeting different regulators such as DNMT3a, TWIST1, ITPR2, AR, and NMT3b." (PMID 35368699, 2022). "AR-independent mechanisms with exceptionally low or absent AR expression found in cancer cells suppress ADT effectiveness and contribute to aggressive variants, including neuroendocrine differentiation." (PMID 36176749, 2022). "Its expression is not noted to change in cancer progression but it does regulate AR activity as both a co-activator and co-repressor and affect fibroblast adhesion and motility." (PMID 37435460, 2022). "In summary, albeit sparseness of the material in the needle biopsies, we observed that a majority of the stroma in proximity to non-responding cancer cells pre-ADT lacks AR to a higher extent, in all patients." (PMID 36115838, 2022). "Downregulation of EZH2, AR, and PSA expression in all tested PCa cells by the Myc inhibitor 10058-F4 suggests that HSP60 may regulate these cancer-promoting proteins via c-Myc." (PMID 35653190, 2022). "With numerous inhibitors of PI3K and mTOR already FDA approved, an obvious next step would be to investigate whether co-targeting AR and either PI3K or mTOR results in synergistic anti-cancer activity." (PMID 35650195, 2022). "However, evidence is accumulating that it can act as a transcriptional coactivator of genes involved in the development of various types of cancer, such as c-Myc, cyclin D1, CXCR4, IL6, TNF, IGF1R, MMPs, and AR." (PMID 36362406, 2022). "The complex interplay between DNA repair, PARP, and AR, can potentially be exploited with combination therapeutic strategies to enhance DNA damage and cancer cell death, even amongst cancers without HRR alterations." (PMID 36497408, 2022). "Interestingly, AR (or ESR1) silencing also blocked SG formation after ARPI (or ERPI) stress in prostate (and breast) cancer cells, highlighting a role for AR and ESR1 mRNA in triggering SGs when its receptor is antagonised." (PMID 34939643, 2022). "In particular, the inability of cancer cells to activate the ATF4/CHOP pathway was a constant feature of THEM6‐deficient PCa cancer cells, irrespective of their AR status." (PMID 35014179, 2022). "This is particularly evident form the significant reduction in nuclear mTOR, pmTOR and AR, but slight/moderate to no reduction in cytoplasmic mTOR and AR in PCa and other cancer cells upon miR-99b-5p mimic transfection." (PMID 36077039, 2022). "Furthermore, several genes with higher expression in PC were looped to cancer-specific active enhancers and included binding sites for PC signature TFs, such as FOXA1 and AR." (PMID 34283056, 2021). "Cancers being ER/PR/HER2 negative but AR positive showed better outcome compared to those AR negative." (PMID 34066838, 2021). "In conditions in which AR expression decreases, IL-6 expression may increase, thus leading to increased phosphorylation of STAT-3 and appearance of cancer stem cells." (PMID 34204596, 2021). "In addition, another study has identified that USP22 is a major effector of AR levels, AR output, AR-MYC coordination, and the transition to CRPC to drive a lethal cancer progression." (PMID 34548474, 2021). "Considered together, our work highlights how coupling between Notch, EMT and PAGE4/AR signaling pathways can give rise to non-trivial dynamics and non-genetic heterogeneity in a cancer cell population." (PMID 33652914, 2021).
cancer (continued). "Finding new treatments for CRPC that are independent of the AR is critical due to the emergence of AR- cancers following the use of AR-antagonists such as enzalutamide and bicalutamide." (PMID 34681244, 2021). "AR, Ki67 and HF1beta were more strongly expressed in cancer cells than in stroma, VEGF was almost equally expressed in both, while MMP9 was more strongly expressed in stroma than cancer cells." (PMID 33920263, 2021). "Androgen receptor (AR) and histone deacetylase 6 (HDAC6) are important targets for cancer therapy." (PMID 33621955, 2021). "EZH2 or AR inhibitors alone did not demonstrate significant anti-cancer efficacy, and easily induced drug resistance due to the reciprocal feedback activation loop." (PMID 34977151, 2021). "In addition to spontaneously arising cancers, carcinogen-driven UBC in mice were accelerated by AR and androgens." (PMID 34768683, 2021). "Gene ontology from RNA-seq results also confirmed the additional functions of AR in cell cycling/proliferation particularly by regulating Hippo, PI3K/Akt and MAPK signaling pathways which can all contribute to both CSC and differentiated cancer cell divisions." (PMID 34094902, 2021). "ER and PR are members of the sex steroid hormone receptor family, including the androgen receptor (AR); however, only ER and PR are used for cancer classification, while AR is not." (PMID 34070921, 2021). "It is also noteworthy that the cSC population was enriched for genes involved in ligand-independent androgen receptor signaling, IGF-1 receptor signaling, autophagy, and HIF-1 targets, thus identifying potential therapeutic targets for this unique cancer cell type." (PMID 34360875, 2021). "None of the cancer cells in these 3 PDXs express AR protein, thus explaining why they are resistant to ARSis." (PMID 33724955, 2021). "Cancer cells from this biopsy had no detectable AR, downregulated an AR-regulated gene set and upregulated a NEPC gene set 17,18." (PMID 33664492, 2021). "AR, IGF1R, PDGFRB, PIK3R1, and SUFU involved in KEGG pathways in cancer." (PMID 34208639, 2021). "There is a positive correlation between TERF1 and androgen receptor expression in cancer tissue (r = 0.53, p < 0.00001) but not on normal tissue (r = - 0.16, p = 0.12)." (PMID 34486082, 2021). "It is well established that the expression of AR differs according to molecular subtypes of BC with more frequent expression in ER negative cancers." (PMID 35047068, 2021). "A possible explanation is that the cancer-initiating cells in these DN-PDXs are derived from transformed progenitor cells that never expressed AR and thus are unresponsive to AR-targeted therapy." (PMID 33724955, 2021). "Furthermore, the activation of selective AR subtypes has been related to the promotion of the epithelial–mesenchymal transition (EMT) in GBM and other types of cancer." (PMID 33081024, 2020). "Super‐enhancers are major regulators of oncogene expression in different cancer types but the impact of AR antagonists on their function has not been explored yet." (PMID 32333502, 2020). "Different expression and activation levels of GLI3-FL regulators (SPOP, androgen receptor, PP2A, CBP, SET7, MED12) or regulators of GLI3-R (PKA, GSK3β, βTrCP) in cancer cells in comparison to healthy cells might also promote cancer cell growth and survival." (PMID 32245491, 2020). "For the cancer types that performed the worst, liver hepatocellular carcinoma included none of the used oncogenes (AR, KLF4, PDGFRA, and RET) or tumor suppressors (BRCA2, CDKN2A, and TSC1) that were linked to it." (PMID 31900418, 2020). "In this stage cancer cells are able to proliferate independent of testosterone mostly through androgen-independent AR signaling." (PMID 32714315, 2020). "All other cancers, which do not express or require AR, had the same signature at both the ARBS and whole genome." (PMID 32047165, 2020).
cancer (continued). "Moreover, they documented that quercetin regulated the expression of androgen receptors (AR), protein kinase B (AKT), insulin-like growth factor receptor 1 (IGFIR), and cell proliferation and anti-apoptotic proteins that are increased in cancer." (PMID 32210182, 2020). "By multivariate survival analysis, Sox2 was a robust pejorative prognostic factor (HR = 1.48, 95% CI 1.04–2.11, p = 0.0292), independent of cancer stage at diagnosis, and independent of AR, whose prognostic value was favorable (p < 0.0001 for the model)." (PMID 33553286, 2020). "To this end, we used novel computational models that measure functional activity of oncogenic signaling pathways, which have been developed over the past decade for activity assessment of the AR, ER, PI3K-FOXO, HH, NFκB, TGFβ and Wnt pathways based on analysis of mRNA from cancer tissue." (PMID 32230714, 2020). "An increase in mutations at ARBS was clearly observed in PCa, but not other cancers, with a enrichment ~ ± 375 bp from the maximal AR peak." (PMID 32047165, 2020). "Since AR is known to inhibit apoptosis induced by cytotoxic stimuli, we measured the levels of apoptotic proteins in KDM7A knock-down cells treated with the anti-cancer drug cisplatin." (PMID 32781788, 2020). "One of the interesting findings was that 7% of reported fall cases were attributable to cancer treatment interruption, including chemotherapy and/or androgen deprivation therapy, but not reported with androgen receptor blocker agent interruption." (PMID 33201234, 2020). "We did not identify any hormone-sensitive cancers harboring a low AR-MethSig median methylation ratio." (PMID 32149736, 2020). "Given that BET family proteins interact with AR, BET inhibitors could be an alternative strategy for targeting AR-driven cancers." (PMID 31527644, 2019). "Concerning MacroH2A1.2, all AR+ PCa cell lines (22Rv1, LNCaP and VCaP) displayed significantly higher expression levels than the benign prostate cell line (p < 0.01, for all) whereas AR− cancer lines did not disclose significant differences compared to RWPE-1." (PMID 31164793, 2019). "Inhibition of CK2 or its molecular downregulation results in cancer cell death, including AR-positive and -negative PCa cells." (PMID 31197122, 2019). "There was a strong and linear increase of SNW1 with increasing AR expression: Only 2% of AR-negative, but 25% of cancers with strong AR expression showed strong SNW1 expression (p < 0.0001)." (PMID 31043167, 2019). "In accordance to our findings, CD300LG was found to be down-regulated in AR+ TNBC tissues when compared with adjacent normal studies, but its role in cancer is still unknown." (PMID 31238876, 2019). "Our data demonstrate that AR signaling can regulate the “cadherin switch” in bladder nonmalignant transitional epithelial cells and cancer cells." (PMID 31119584, 2019). "Nonetheless, no radical treatments exist at present and all AR-targeting agents for CRPC eventually fail to suppress cancer cell activity." (PMID 30871130, 2019). "There was a strong positive association between AR expression and ROCK1 expression in all cancers as well as in subsets of ERG negative and ERG positive cancers." (PMID 31557128, 2019). "Taken together, it becomes evident that recurrent cancers after medical or surgical castration are not truly androgen-independent, as they continuously depend on androgens and the androgen receptor to survive and grow." (PMID 31552182, 2019). "Studies have shown that ER negative cancers do respond to AR blockade therapy suggesting a role for AR in prognosis." (PMID 31749762, 2019). "Importantly, the key cancer-drivers/oncogenes MYC, MYB and AR were suppressed by TSPX in a CAD-dependent manner." (PMID 30863497, 2019). "Although further research is needed to elucidate non-genomic AR signaling in endothelial cells, it is remarkable that NO production supports immune suppressive microenvironment, enhancing cancer growth." (PMID 31616657, 2019).
cancer (continued). "Upon examination of AR-modulatory miR levels in fresh-frozen tissue from five PCs and six normal prostates (GSE34932), it was found that miR-197 was significantly decreased in cancer vs normal, while miR-361-3p is unchanged and miR-346 significantly increased." (PMID 31043708, 2019). "Activation of androgen/AR genomic and non-genomic signaling probably is not a driver in male bladder oncogenic transformation, but is a major player in progression of those cancers." (PMID 31119584, 2019). "With advances in immunotherapy and fluid biopsies for cancer management, expression systems specific for both AR-positive and -negative PCa are required for virus-based vaccines and cell imaging." (PMID 30626088, 2019). "For certain receptors such as AR and ERα, their pro-oncogenic roles in CAF could be dependent on the cancer types and biochemical signals, resulting in the contradictory findings obtained thus far." (PMID 30925918, 2019). "The androgen receptor is involved in the initiation and progression of various types of cancers (bladder, kidney, lung, breast, and liver, but not the prostate, where it acts as a suppressor)." (PMID 31100850, 2019). "Androgen-receptor-negative canine PC is a complex disease characterized by high genomic instability, showing a set of genes with similar alterations to human cancer." (PMID 30925701, 2019). "In addition, AR exerts dual regulatory effects on SRARP, and although an increased AR activity suppresses SRARP transcription, a minimum level of AR activity is required to maintain baseline SRARP expression in AR+ cancer cells." (PMID 29577611, 2018). "Since advanced cancer has a poor prognosis with a limited response to surgery and radiation therapy, development of new treatment strategies, such as molecular-targeting therapies directed against HER-2 and AR, is required." (PMID 29564569, 2018). "We observed positive staining for the three antibodies in all epithelial samples, which is remarkable since benign tumors (like BPH) and primary cancer are not expected to express AR-Vs, which are supposed to arise only after androgen deprivation therapy." (PMID 30028845, 2018). "However, the major strategic advance for thetreatment of CRPC is the realization that the AR is still functional in CRPC and, like inbreast cancer, remains a potential target." (PMID 29162647, 2018). "There are multiple mechanisms involved in the development of the androgen-independent phenomenon that enables the cancerous cells to activate the androgen receptor (AR) in the absence of androgens, or recruit other receptors to facilitate cancer progression." (PMID 30241348, 2018). "AR was present at a lower level in the Krt5 positive invasive cancer, and was clearly absent from stromal cells." (PMID 29782499, 2018). "Our data provides new information suggesting that AR, EGFR and MMP-9 are interconnected and may play important roles during cancer progression from androgen-dependent state to castration-resistant state." (PMID 30134822, 2018). "Prognostic and predictive biomarkers for NEtD and NEPC are in dire need since ADT is not effective for a cancer that has undergone NEtD and thus circumvents the AR signalling axis." (PMID 29757368, 2018). "Herein, our GSEA analyses confirmed that phospho-PRs significantly induce expression of HER2-associated gene sets and demonstrated that phospho-PR target genes also include key mediators of cancer stem cell biology, including PAX, AHR, AR, and RUNX family members." (PMID 28412963, 2017).
cancer (continued). "CYT997 inhibited proliferation and viability of all these cells in a dose-dependent manner, suggesting that CYT997 exhibits inhibitory effects on cancer growth and survival regardless of AR expression." (PMID 28606127, 2017). "The correlation between AR and FOXA1 mRNA expression in the METABRIC dataset was moderately positive (Pearson r = 0.424; p < 0.001) in ER-positive cancers and strongly positive (Pearson r = 0.777; p < 0.001) in ER-negative cancers." (PMID 29137314, 2017). "AR is an attractive target with or without anti-cancer drugs in HCC, one of the male dominant diseases." (PMID 28475115, 2017). "High-level GGH expression was found in 19.9% of cancers without detectable AR expression, but in 44.6% of tumors with strong AR expression (p < 0.0001, each)." (PMID 28146062, 2017). "It was proposed that DNA damage give rise to mRNA splicing by post-translational modification of splicing factor and alternative splicing of the components of the two critical pathways in PCa, AR and PI3K, was involved both in cancer development and in therapy escape." (PMID 29216878, 2017). "However, the expression of AR in AMACR− cancer cells was remarkably stronger than in either AMACR+ cancer cells or AMACR− benign epithelial cells, whereas AMACR+ cancer cells and AMACR+ benign luminal cells showed similar AR expression." (PMID 29138507, 2017). "To demonstrate this, we detected and automatically classified 83,558 cells in the whole tissue section as stromal, basal epithelial, benign luminal epithelial, or cancer cells, and then measured the expression of CK8, CK18, AMACR and AR in all the cells quantitatively." (PMID 29138507, 2017). "The standard treatment for PCa is to block transcriptional activity of androgen receptor using androgen deprivation therapy (ADT), which invariably results in the development of a more aggressive form of cancer (called castration-resistant PCa or CRPC) with restored activity of AR." (PMID 28036278, 2017). "Again co-expression of AR on different subtypes of cancers (ER, HER2 or in TNBC) are not well studied." (PMID 29254284, 2017). "Interestingly, metformin’s biological effects are not limited to inhibiting cancer proliferation, but include effects on epithelial to mesenchymal transition (EMT), bone turnover, the androgen receptor, and cancer stem cells." (PMID 28444639, 2017). "Different non-steroidal androgen receptor antagonists are approved also in the case of castration-resistant cancer forms." (PMID 30108852, 2017). "Interestingly, we found that AR expression was 43% higher in AMACR− cancer cells (n = 11,511) than in AMACR+ cancer cells (n = 5,103) (0.160 vs. 0.112, p < 0.001) and 58% higher than in AMACR− benign luminal cells (n = 9,068) (0.160 vs. 0.101, p < 0.0005)." (PMID 29138507, 2017). "It is difficult to postulate why documented changes in AR expression in cancer was not mirrored in our exoRNA study except that perhaps AR expression is not governed at the mRNA level but rather at the protein level." (PMID 27144529, 2016). "In cancer cells ATAD2 has been proposed to function as a transcriptional co-regulator of several oncogenic transcriptional factors including estrogen receptor (ER), androgen receptor (AR), E2F transcriptional factor and Myc." (PMID 27612420, 2016). "As with many other cancer types, resistance to therapy occurs in PCa in the form of progression to advanced castration-resistant prostate cancer (CRPC) and is accompanied by reactivation or maintenance of AR signaling, which triggers a unique AR transcriptome." (PMID 26657335, 2016). "Crosstalk between AR and SRC has been observed in human cancer." (PMID 27028864, 2016). "Twelve (10.3%) of the 117 TNBC from noncarriers had co-expression of AR and PD-L1 on cancer cells, 5 with weak AR staining and 7 with >10% AR staining (data not shown)." (PMID 28721372, 2016).